GSTZ1 (glutathione S-transferase zeta 1)
Diseases named in the same sentence as GSTZ1 in open-access papers (continued):
Sharing a sentence is not in itself a finding about the gene and the disease.
bipolar disorder (2 papers, 2020 to 2022). A disorder of the brain that causes unusual shifts in mood, energy, activity levels and the ability to carry out day-to-day tasks. "Another related study found that polymorphisms in the GSTZ1 gene were associated with early-onset susceptibility to bipolar disorder." (PMID 35893077, 2022). "An association was shown between variants in GSTZ1 and an increased susceptibility to early onset of bipolar disorder." (PMID 32507125, 2020).
Cirrhosis (2 papers, 2024 to 2025). A chronic disorder of the liver in which liver tissue becomes scarred and is partially replaced by regenerative nodules and fibrotic tissue resulting in loss of liver function. "Furthermore, the liver tissues of patients with liver failure and hepatic cirrhosis exhibited downregulated expression of CBS, CYP1A2, FOXA1, GSTZ1, WDR72 and UHMK1 when compared to healthy controls." (PMID 38287425, 2024). "Notably, the expression of FOXA1, GSTZ1, WDR72 and UHMK1 was more upregulated in the tissues of individuals with hepatic cirrhosis than those with liver failure, although statistical significance was not achieved." (PMID 38287425, 2024).
glioma (2 papers, 2022 to 2023). A benign or malignant brain and spinal cord tumor that arises from glial cells (astrocytes, oligodendrocytes, ependymal cells). "When analyzing similar data regarding GSTZ1 in the CGGA database, we did not obtain the results that suggested any significant correlations between GSTZ1 expression and glioma status." (PMID 36291099, 2022). "In addition, TAT and glutathione S‐transferase zeta 1 (GSTZ1) also slightly promotes the malignant phenotype of gliomas." (PMID 37786553, 2023).
renal carcinoma (2 papers, 2022 to 2023). A carcinoma arising from the epithelium of the renal parenchyma or the renal pelvis. "At the molecular level, we found that SLC2A1, LDHA, GOT1, and GOT2 were regulated by HGD and GSTZ1 to alter the glucose uptake and energy metabolism of renal cancer cells." (PMID 35562974, 2022). "Mechanistically, we found that decreased HGD and GSTZ1 regulate amino acid metabolism to reduce fumarate production, which in turn remodels metabolic flux and energy production in renal cancer cells, ultimately promoting cell cycle and proliferation." (PMID 35562974, 2022). "Wang J and his research team illustrated that two enzymes involved in tyrosine metabolism, homogentisate 1,2-dioxygenase (HGD), and glutathione S-transferase zeta 1 (GSTZ1) were downregulated in three renal cancer types (KIRC, KIRP, and KICH) of tissues versus healthy ones." (PMID 37176098, 2023). "However, the mutation rate of HGD and GSTZ1 was only 0.7% in KIRC, indicating that the function of HGD and GSTZ1 in renal cancer depends on the expression abundance." (PMID 35562974, 2022). "Not only that, but consistent with previous studies, energy-generating pathways (glycolysis, TCA cycle, and OXPHOS) in renal cancer cells were inhibited due to the reduction of HGD and GSTZ1." (PMID 35562974, 2022). "We believe that the tyrosine metabolizing enzymes HGD and GSTZ1 are reliable biomarkers of KIRC, which will provide important help for the clinical diagnosis and treatment of renal cancer." (PMID 35562974, 2022). "Therefore, we analyzed the prognostic correlation of tyrosine metabolizing enzymes in three renal cancers and found that TAT, HGD, and GSTZ1 were correlated with the prognosis of KIRC, while GSTZ1 was significantly correlated in KIRP." (PMID 35562974, 2022).
renal cell carcinoma (2 papers, 2022 to 2024). "Glutathione S-transferase zeta 1 (GSTZ1) has been clearly described in some types of cancers, such as HCC and renal cell carcinoma." (PMID 38287425, 2024).
Chronic Myeloid Leukemia (1 paper, 2020). "Most importantly, overexpression of GSTZ1 in HCC cell led to the downregulation in several pathways in cancer gene sets (Kegg Small Cell Lung Cancer and Kegg Chronic Myeloid Leukemia)." (PMID 32542016, 2020).
complication (1 paper, 2024). Any disease or disorder that occurs during the course of, or because of, another disease, treatment, or procedure. "In the tibial artery, genetically predicted increased expression of GSTZ1 and PCK2 was causally linked to an increased risk of peripheral circulatory complications in T2DM patients, while HAGH exhibited an opposite causal effect." (PMID 39280009, 2024).
glaucoma (1 paper, 2023). Increased pressure in the eyeball due to obstruction of the outflow of aqueous humor. "Of most significant coding variants associated with increased risk of glaucoma medication non-adherence, rs2272487 (CHCHD6), rs7975 (GSTZ1), and rs11591349 (SEMA4G) were identified by MPR80." (PMID 36982708, 2023).
Hypoglycemia (1 paper, 2024). A decreased concentration of glucose in the blood. "In sharp contrast, Fah−/− mice treated with rAAV8-SaCas9 targeting either Hgd or Gstz1 experienced sudden weight loss and hypoglycemia and died approximately 4 and 5 days post-NTBC removal, respectively." (PMID 39178380, 2024).
Kidney Clear Cell Carcinoma (1 paper, 2022). "To uncover the functional mechanism of HGD and GSTZ1 in KIRC, we utilized the publicly available datasets (The Cancer Genome Atlas-Kidney Clear Cell Carcinoma) for pathway enrichment analysis." (PMID 35562974, 2022).
leukemia (1 paper, 2022). A malignant (clonal) hematologic disorder, involving hematopoietic stem cells and characterized by the presence of primitive or atypical myeloid or lymphoid cells in the bone marrow and the blood. "To validate the function of SETD1A target genes (COX15, HMBS, UROS, RRNAD1, NUDT18, GSTZ1, HINT2, and COX18) in leukemia cells, we performed a CRISPR-based competitive cell proliferation assay in doxycycline-inducible Cas9-expressing MOLM-13 leukemia cells." (PMID 36450243, 2022).
liver fibrosis (1 paper, 2024). "Nevertheless, the specific mechanism of GSTZ1 in the progression of liver fibrosis still requires additional investigation." (PMID 38287425, 2024). "We found that GSTZ1 may have a protective role in the onset and progression of liver fibrosis." (PMID 38287425, 2024). "According to the validation of clinical specimens, CBS, CYP1A2, FOXA1, GSTZ1, WDR72 and UHMK1 were specifically expressed in patients with liver fibrosis or hepatocirrhosis." (PMID 38287425, 2024). "The mechanism of CBS, CYP1A2, FOXA1, GSTZ1, WDR72 and UHMK1 in the progression of liver fibrosis is still unclear." (PMID 38287425, 2024).
lung squamous cell carcinoma (1 paper, 2025). "Conversely, in lung squamous cell carcinoma, elevated GSTZ1 expression supports tumor cell survival by enhancing the detoxification of reactive aldehydes." (PMID 41474538, 2025).
malignant glioma (1 paper, 2021). A grade III or grade IV glioma arising from the central nervous system. "In a “3 + 3” study design in 15 patients (2 patients with metastatic brain tumors, 13 malignant glioma), DCA dosing was based on haplotype variation in glutathione transferase zeta 1/maleylacetoacetate isomerase (GSTZ1/MAAI), which participates in DCA and tyrosine catabolism." (PMID 34298883, 2021).
skin cutaneous melanoma (1 paper, 2022). "Similar to GSTZ1, high levels of GSTA1 were positively associated with higher OS and DFS in patients with ACC and were potentially associated with prolonged DFS in patients with LUSC, but levels of GSTA1 were only negatively correlated with OS in patients with skin cutaneous melanoma (SKCM)." (PMID 36291099, 2022).
tumor (18 papers, 2014 to 2025). "NTBC decreased GSTZ1 depletion–induced tumor-associated angiogenesis, which was significantly restored by SA treatment." (PMID 37906252, 2023). "Targeting HIF-1α alleviates the tumor-promoting effect of GSTZ1 deficiency in orthotopic mouse models of HCC." (PMID 37906252, 2023). "Decreased GSTZ1‐1 expression was associated with advanced tumor stage in the TCGA database (stage I/II versus stage III/IV, P = 0.005)." (PMID 31267557, 2019). "In contrast, GSTZ1 and GSTA1 generally showed low expression in tumor tissues, which suggests that these enzymes mainly exhibit tumor suppressive effects, and that the reduction in GSTZ1 and GSTA1 levels is associated with poor prognosis of KIRC, ACC, and other tumors." (PMID 36291099, 2022). "Furthermore, Kyoto Encyclopedia of Genes and Genomes analysis showed that GSTZ1 negatively regulates signaling pathways associated with tumour progression, such as TGFβ, FoxO, Wnt and Hippo signaling." (PMID 35979621, 2022). "Our findings may help illuminate the molecular mechanisms underlying the tumour suppressor role of GSTZ1‐1 during HCC development." (PMID 31782257, 2020). "Given our data showing that HIF-1α inhibition alleviates the tumor-promoting effect of GSTZ1 deficiency on HCC angiogenesis, we propose that a therapeutic strategy that suppresses SA-activated HIF-1α may improve current therapies that have limited effect on abnormal vasculature." (PMID 37906252, 2023). "The results showed that Gstz1-KO promoted HCC progression, whereas 2-ME2 treatment significantly decreased the proliferation of parental and Gstz1-KO cells in vivo based on tumor number and liver-to-body weight ratio." (PMID 37906252, 2023). "Gstz1–/– mice exhibited liver tumorigenesis with an increased number of tumor masses and tumor nodules." (PMID 37906252, 2023). "Our study found marked accumulation of SA in GSTZ1-deficient HCC and demonstrated the role of abnormal accumulation of SA in controlling tumor angiogenesis and vessel abnormalities." (PMID 37906252, 2023). "To investigate how GSTZ1 impairs the observed tumour metastasis, we performed a global transcriptomic analysis of GSTZ1‐OE Huh7 cells." (PMID 35979621, 2022). "More importantly, this is the first report of the amino acid metabolizing enzymes HGD and GSTZ1 as tumor biomarkers." (PMID 35562974, 2022). "In this study, we found that the abilities of GSTZ1 deficiency‐mediated UGDH up‐regulation, UDP‐GlcUA accumulation, and tumour migration promotion were NRF2 dependent." (PMID 35979621, 2022). "To define the clinical relevance of our findings, we determined the levels of UGDH, GSTZ1, pSmad2/3 and E‐cadherin in tumours from 10 HCC patients with metastatic recurrence." (PMID 35979621, 2022). "We found that β‐catenin was expressed at low levels in the NT but was significantly highly expressed in tumours, exhibiting expression patterns exactly opposite of those of GSTZ1‐1." (PMID 31782257, 2020). "Specifically, HPD staining decreased by 2.26-fold ± 2.10 (p = 0.0388), HGD decreased by 1.67-fold ±0.87 (p = 0.0423) and GSTZ1 decreased by 2.27-fold ±1.09 (p = 0.0007) in HCC tumor compared to normal liver tissue." (PMID 32542016, 2020). "Western blotting and IHC revealed increased levels of NQO1 and decreased levels of GSTZ1 in most tumors, compared to tumor-adjacent normal tissues." (PMID 31666108, 2019). "We further analyzed GSTZ1 mRNA expression in an independent cohort of 363 HCC tissues (including 50 paired tumor and normal liver tissues) from The Cancer Genome Atlas (TCGA) database." (PMID 31267557, 2019). "To evaluate intratumor GSTZ1 deregulation, we compared its expression between tumor tissue and tumor-adjacent normal tissue samples with mRNA-Seq data from TCGA database using Firebrowse." (PMID 31666108, 2019). "GSTZ1 mRNA expression was significantly decreased in tumor tissues compared with normal liver tissues (P < 0.001)." (PMID 31267557, 2019).
tumor (continued). "Our findings suggest that GSTZ1 may serve as an important tumor suppressor owing to its ability to inhibit the HIF-1α/VEGFA axis in HCC." (PMID 37906252, 2023). "In addition, we explored the relationship between the TRGs risk model and TME, and revealed the strong association of METTL6, LCMT1, GSTZ1, ADH4, and ADH1A with the tumor immune infiltration and immune checkpoints." (PMID 36341373, 2022). "This study broadens our understanding of the biological function of GSTZ1‐1, which may be helpful in further elucidating the underlying molecular mechanism by which GSTZ1‐1 acts as a tumour suppressor in the context of HCC." (PMID 31782257, 2020). "In addition, GSTA1, GSTM1, and GSTZ1 are reported to be downregulated in tumor tissue and can correlate with a poor prognosis, while GSTT1, GSTO1, and GSTK1 are mostly reported to be upregulated in tumor tissue compared to the normal surrounding tissue." (PMID 33228209, 2020). "Here, we show that GSTZ1‐1 serves as a tumor suppressor in HCC and provide an alternative mechanism by which an oncometabolite may activate the IGF1R pathway." (PMID 31267557, 2019). "GSTZ1‐1 functions as an important tumor suppressor by inhibiting NRF2/IGF1R axis in HCC." (PMID 31267557, 2019). "Moreover, inhibition of IGF1R or NRF2 significantly inhibited tumor‐promoting effects of GSTZ1 knockout in vivo." (PMID 31267557, 2019). "However, the HIF-1α inhibitor 2-ME2 abrogated the increase in VEGFA, MMP2, and MMP9 induced by GSTZ1 deficiency in orthotopic mouse models, revealing that inhibition of HIF-1α with 2-ME2 substantially reversed tumor growth, MVD, and progression in Gstz1-KO mice." (PMID 37906252, 2023). "Compared with WT mice, Gstz1 knockout significantly reduced the inhibitory effects of sorafenib treatment in vivo than that in WT mice, as indicated by the increased tumor sizes, number of tumor nodules, and a higher level of alanine aminotransferase (ALT) in serum." (PMID 33931597, 2021). "Moreover, our studies demonstrated that GSTZ1‐1 plays a tumor suppressor role in HCC." (PMID 31267557, 2019). "Considering the important role of HIF-1α in angiogenesis, we next investigated the effect of GSTZ1 on HIF-1α expression, tumor progression, and metastasis in orthotopic mouse models of HCC." (PMID 37906252, 2023). "Lower GSTZ1 and E‐cadherin levels and higher UGDH and pSmad2/3 levels were observed in tumour samples than in adjacent non‐tumoural tissues." (PMID 35979621, 2022). "We observed that ADH4, GSTZ1, and ADH1A were downregulated in HCC tumor tissues, while the LCMT1 was overexpressed in HCC tumor tissues compared with the normal tissues, which were consistent with the mRNA expression level of HCC." (PMID 36341373, 2022). "GSTZ1 belongs to the Glutathione S-transferase (GST) superfamily and GSTZ1 has been reported to be downregulated in HCC and performed as a tumor suppressor in the HCC progression, which is in line with our findings." (PMID 36341373, 2022). "GSTZ1 and GSTA1 were also significantly differentially expressed in different stages of 7 and 5 tumor types, respectively." (PMID 36291099, 2022). "ADH4, GSTZ1, and ADH1A were downregulated in HCC tumor tissues compared with the normal tissues, which were consistent with their role in HCC." (PMID 36341373, 2022). "Quantitative RT–PCR (qRT–PCR), Western blotting, and immunohistochemical (IHC) assay revealed that GSTZ1 mRNA and protein expression levels were significantly lower in HCC than in the corresponding non‐tumor tissues." (PMID 31267557, 2019). "In the present study, we found that the expression of GSTZ1‐1 is downregulated in HCC cell lines and tumor tissues, and Gstz1−/− mice showed increased hepatocarcinogenesis following chemical carcinogen exposure." (PMID 31267557, 2019). "The current study revealed that GSTZ1‐1 expression is markedly downregulated in HCC, which contributed to tumor progression and poor prognosis, providing evidence supporting recent reports that GSTZ1‐1 is decreased in HCC." (PMID 31267557, 2019).
tumor (continued). "GSTZ1 and GSTA1 are expressed at low levels in a variety of tumors and may play a role in tumor suppression." (PMID 36291099, 2022). "In summary, we identified the tyrosine metabolizing enzymes HGD and GSTZ1 as biomarkers of KIRC, which will further the understanding of the tumor metabolism profile, provide novel strategies and theoretical support for diagnosing and treating KIRC and as referential for future clinical research." (PMID 35562974, 2022). "Mechanistically, we found that decreased HGD and GSTZ1 promote aerobic glycolysis in KIRC, coordinate the balance of amino acid metabolism and energy metabolism in tumor cells, and ultimately activate the tumor cell cycle and tumor progression." (PMID 35562974, 2022). "To further investigate the clinical relevance of GSTZ1‐1 and the Wnt/β‐catenin pathway, we performed IHC analyses to assess the co‐existence of GSTZ1‐1 and β‐catenin in paired tumour and nontumour liver tissues from patients." (PMID 31782257, 2020). "To confirm this observation, we conducted RT-qPCR analysis using 40 tumor samples from HCC patients to detect GSTZ1 and NQO1 mRNA expression, and we observed a negative correlation between GSTZ1 and NQO1 expression (r = − 0.37, p = 0.0197)." (PMID 31666108, 2019). "Further, we examined GSTZ1 expression in 16 paired clinical HCC and normal liver tissue samples via IHC and Western blotting, which revealed that GSTZ1 was significantly downregulated in HCC rather than tumor-adjacent normal tissue." (PMID 31666108, 2019). "In this study, we have found that HGD and GSTZ1 regulate the level of fumarate by metabolizing tyrosine, and by affecting GOT1 and GOT2 to coordinate amino acid metabolism and energy metabolism, determine the energy production pathway of tumor cells, and ultimately regulate the cell cycle." (PMID 35562974, 2022). "Importantly, no articles have reported HGD and GSTZ1 as potential biomarkers of KIRC, so our study is the first to identify HGD and GSTZ1 as tumor biomarkers, which fills the gap of tyrosine metabolism in the field of tumor markers." (PMID 35562974, 2022).